SPMIP1 (sperm microtubule inner protein 1)
Synonyms: ATP6V1FNB
Gene: Protein-coding gene on chromosome 7 (128,866,330 to 128,872,047, forward strand). Ensembl gene ENSG00000272899.
Genetic constraint (gnomAD): Loss-of-function variants: 14 observed, 17.36 expected, observed/expected ratio (o/e) 0.81, 90% interval 0.53 to 1.26. The upper end of that interval is the gene's LOEUF score, 1.26, which puts it in group 5 of 6, group 1 being the genes least tolerant of losing a copy. Missense variants: 228 observed, 232.85 expected, observed/expected ratio (o/e) 0.98, 90% interval 0.88 to 1.09. Synonymous variants: 74 observed, 97.16 expected, observed/expected ratio (o/e) 0.76, 90% interval 0.63 to 0.92.
Homologues: Orthologues: chimpanzee SPMIP1 (98% identical), macaque SPMIP1 (94% identical), dog SPMIP1 (90% identical), guinea pig SPMIP1 (89% identical), rabbit SPMIP1 (88% identical), pig SPMIP1 (84% identical), mouse Spmip1 (82% identical), rat Spmip1 (66% identical), tropical clawed frog spmip1 (33% identical).